MGP (matrix Gla protein)
Diseases named in the same sentence as MGP in open-access papers (continued):
Sharing a sentence is not in itself a finding about the gene and the disease.
thyroid cancer (2 papers, 2022 to 2024). "C/EBPα and MGP expression exhibited a significant inverse correlation in bile duct, bladder, and esophageal cancers and a positive correlation in breast, colorectal, lung, and thyroid cancers." (PMID 39684309, 2024). "MGP expression was positively closely related to GATA1 in bladder, breast, colorectal, esophageal, head and neck, kidney, liver, lung, prostate, and thyroid cancers." (PMID 39684309, 2024). "According to the documented literature and our data, the positivity of MGP, GATA3, and TRPS1 is extremely rare in other tumor types, such as cholangiocarcinoma and colorectal, gastric, and thyroid carcinomas." (PMID 36284362, 2022).
type 1 diabetes (2 papers, 2010 to 2018). "This is consistent with the high MGP mRNA expression observed in atherosclerotic vessels and plaques in patients with type 1 diabetes." (PMID 21143859, 2010).
ulcerative colitis (2 papers, 2022 to 2024). An inflammatory bowel disease involving the mucosal surface of the large intestine and rectum. "Compared with the normal group, the expression of SGK1, CEP55, ACSL1, OLFM4, and MGP was markedly increased in the DSS‐induced ulcerative colitis group." (PMID 34939750, 2022). "Our findings indicated that DPP10, MST1L, DPP10‐AS1, CEP55, ACSL1, MGP, OLFM4, and SGK1 may act as diagnostic biomarkers for ulcerative colitis and that differential immune infiltration cells may help to illustrate the progression of ulcerative colitis." (PMID 34939750, 2022).
acute kidney injury (1 paper, 2020). Sudden and sustained deterioration of the kidney function characterized by decreased glomerular filtration rate, increased serum creatinine or oliguria. "miR-155-5p enhances oxalate- and calcium-triggered kidney oxidative stress injury by repressing matrix gla protein (MGP) expression and aggravating both inflammation and apoptosis in acute kidney injury tissues via the Jak2/Stat3 pathway." (PMID 33457405, 2020).
aneurysm (1 paper, 2022). Bulging or ballooning in an area of an artery secondary to arterial wall weakening. "MYH11, COL1 (collagen-1), and MGP were detected to show the characteristics of the mural cells in aneurysms." (PMID 35874788, 2022). "Apparently, MYH11and MGP are mostly enriched in IA, COL1 was comparable in both aneurysms, whereas OPN was observed to be high in BBAs but low in IAs." (PMID 35874788, 2022).
asthma (1 paper, 2009). "The genes involved in the classification were: MGP, Abca2, and Sult1a1, which demonstrated that the transportation and production of steroid hormone may be regulated by acupuncture in the EAR phase of asthma at the level of transcription." (PMID 19419550, 2009).
astrocytoma (1 paper, 2025). "FeaturePlots confirmed upregulation of select ECM glycoprotein genes, including IGFBP2 and MGP, in the GBM sample versus grade III astrocytoma." (PMID 41366031, 2025).
atrial fibrillation (1 paper, 2024). A disorder characterized by an electrocardiographic finding of a supraventricular arrhythmia characterized by the replacement of consistent P waves by rapid oscillations or fibrillatory waves that vary in size, shape and timing and are accompanied by an irregular ventricular response. "Furthermore, some drugs such as vitamin K antagonists used in patients with end-stage CKD and atrial fibrillation appear to be involved in VC, through mechanisms that include matrix Gla protein (MGP) inhibition and the γ-carboxylation of other proteins that regulate mineralization." (PMID 39684805, 2024).
brain tumor (1 paper, 2009). "Furthermore, BMPs inhibit the tumorigenic potential of human brain tumor-initiating cells, so that MGP-induced repression of BMP signalling may retain tumor cells in an undifferentiated state with enhanced migration potential." (PMID 19712474, 2009).
central obesity (1 paper, 2020). "Taken all together, our data reveals for the first time that MGP plays important role in fat metabolism, and sheds light on the potential of dp-ucMGP as a novel serum marker for central obesity." (PMID 32000575, 2020).
cervical intraepithelial neoplasia (1 paper, 2018). "In the same study, they could also observe elevated MGP expression only in the lower layers of epithelium of high grade cervical intraepithelial neoplasia (CIN) lesions." (PMID 30257426, 2018).
cervical squamous cell carcinoma (1 paper, 2018). A squamous cell carcinoma arising from the cervical epithelium. "In samples with cervical squamous cell carcinoma (SCC), clear cytoplasmic MGP staining was seen in the tumor cells but in cells seen at the borders of the tumor fields the staining was more intense." (PMID 30257426, 2018).
cholangiocarcinoma (1 paper, 2022). A carcinoma that arises from the intrahepatic biliary tree (intrahepatic cholangiocarcinoma) or from the junction, or adjacent to the junction, of the right and left hepatic ducts (hilar cholangiocarcinoma). "Rare cases (0.6–5%) had focal MGP expression in renal, ovarian, lung, urothelial, and cholangiocarcinomas." (PMID 36284362, 2022).
chronic obstructive pulmonary disease (1 paper, 2019). A chronic and progressive lung disorder characterized by the loss of elasticity of the bronchial tree and the air sacs, destruction of the air sacs wall, thickening of the bronchial wall, and mucous accumulation in the bronchial tree. "Elastin degradation is accelerated in chronic obstructive pulmonary disease (COPD) and is partially regulated by Matrix Gla Protein (MGP), via a vitamin K-dependent pathway." (PMID 31357639, 2019).
Cognitive impairment (1 paper, 2023). Abnormal cognition is characterized by deficits in thinking, reasoning, or remembering. "For example, the matrix Gla protein gene (MGP), as a candidate gene, is implicated in the pathogenesis of tooth loss and cognitive impairment through the encoding of the expressed vitamin K binding protein." (PMID 37513507, 2023).
depression (1 paper, 2019). "Nevertheless, in our study, another limitation is the lack of measurement of the uncarboxylated fraction of osteocalcin and matrix gla protein, markers of vitamin K status, which could better account for the real effect of vitamin K on depression and bone health." (PMID 30959758, 2019).
diabetic neuropathy (1 paper, 2020). A chronic, pathological complication associated with diabetes mellitus, where nerve damages are incurred due to diabetic microvascular injury involving small blood vessels that supply these nerves, resulting in peripheral and/or autonomic nerve dysfunction. "Further studies are warranted to precise if circulating MGP is a biomarker and/or a causal factor of diabetic neuropathy." (PMID 32092076, 2020). "Consequently, an excess of inactive form of MGP (i.e., dp-ucMGP), could be associated with nerve damage and a source of axon regeneration loss, two pathological conditions observed in diabetic neuropathy." (PMID 32092076, 2020). "Then fundamental experiments and prospective clinical studies are needed to clarify the role of MGP in diabetic neuropathy, and if this protein could be used as biomarker or as therapeutic target in diabetic neuropathy via vitamin K supplementation." (PMID 32092076, 2020). "Given that the pathogenesis of diabetic neuropathy remains unclear and that MGP could be involved in nervous system pathophysiology, we hypothesize that MGP may be involved in diabetic peripheral neuropathy development." (PMID 32092076, 2020). "Depending on the results of these studies, MGP could be used in diabetic neuropathy for diagnosis, prediction or therapeutic purposes via vitamin K supplementation." (PMID 32092076, 2020).
dilated cardiomyopathy (1 paper, 2018). Cardiomyopathy which is characterized by dilation and contractile dysfunction of the left and right ventricles. "Cardiac biopsies from patients with ischemic or dilated cardiomyopathy and healthy hearts (n = 4 for each) were stained with conformation-specific MGP antibodies." (PMID 29529056, 2018).
disc degeneration (1 paper, 2022). "Chondrocytes 2 expressing MGP, MT1G, and GPX3 may play a role in reversing calcification and degeneration, and chondrocytes 4 expressing PTGES, TREM1, and TIMP1 may play a role in disc degeneration pain and inflammation." (PMID 35874809, 2022).
endometrioid adenocarcinoma (1 paper, 2018). An adenocarcinoma characterized by the presence of malignant glandular epithelial cells resembling endometrial cells. "Additionally, in the endometrioid adenocarcinoma, we could observe two subpopulations of cancer cells with different levels of MGP protein expression (high and weak/moderate)." (PMID 30257426, 2018). "Additionally, in the endometrioid adenocarcinoma we could observe subpopulations of cancer cells with different levels of MGP protein expression (high and weak/moderate)." (PMID 30257426, 2018).
endometriosis (1 paper, 2022). The growth of functional endometrial tissue in anatomic sites outside the uterine body. "The significant increase in the MGP+ stromal subcluster in endometriosis is also of potential interest." (PMID 36104692, 2022). "The MGP+ stromal cell subcluster expresses many genes that are associated with the extracellular matrix, including FN1 (encoding fibronectin-1) which has been associated with an increased risk for endometriosis in GWAS studies." (PMID 36104692, 2022).
endometritis (1 paper, 2020). An acute or chronic, usually bacterial infectious process affecting the endometrium. "The results revealed the dysregulation of the six crucial biomarkers involved in endometritis: SLC7A5, COL1A1, AXIN2 (upregulated); CFD, MGP, CCDC3 (downregulated)." (PMID 32545766, 2020). "This study confirmed differences in the expression profiles of six biomarkers in LPS-induced bovine endometritis: SLC7A5, COL1A1, AXIN2 (upregulated) and CFD, MGP, CCDC3 (downregulated)." (PMID 32545766, 2020).
esophageal cancer (1 paper, 2024). A primary or metastatic malignant neoplasm involving the esophagus. "Next, we performed an in silico analysis and, by doing so, found that YY1 and MGP expression exhibited a significant inverse correlation in the bladder and esophageal cancers." (PMID 39684309, 2024).
fibromatosis (1 paper, 2022). A poorly circumscribed neoplasm arising from the soft tissues. "Interestingly, fibromatosis-like metaplastic carcinomas (FMCs) in our cohort were all positive for MGP (8/8)." (PMID 36284362, 2022).
fibrosis (1 paper, 2024). the formation of excess fibrous connective tissue in an organ or tissue in a reparative or reactive process. "Immunohistochemical analysis of MGP showed positive staining in submucosal fibrosis in both CD and UC as well as subserosal fibrosis of CD, but no staining in the subserosa of UC." (PMID 38877292, 2024).
hand osteoarthritis (1 paper, 2019). "In a genome-wide association study, an SNP significantly associated with hand osteoarthritis was found near matrix Gla protein (MGP) gene, coding one of the substrates of GGCX." (PMID 31212662, 2019).
hemorrhage (1 paper, 2019). Loss of blood from the vascular compartment to the exterior or into nonvascular body space as a result of rupture or severance of the blood vessels. "To investigate the reproductive function of the VKD proteins GGCX and MGP in vivo, we established a warfarin-induced VK2-deficient rat model by using a modified protocol supplemented with VK1 to avoid VK1-deficiency-induced hemorrhage." (PMID 30981116, 2019).
hepatocellular carcinoma (1 paper, 2022). A malignant tumor that arises from hepatocytes. "MGP showed mild-to-moderate positive expression in normal hepatocytes, renal tubules, as well as 31.1% (99/318) of hepatocellular carcinomas." (PMID 36284362, 2022). "Interestingly, we observed that MGP was constantly expressed in normal hepatocytes, but the positive expression was detected in only 31.1% of hepatocellular carcinomas." (PMID 36284362, 2022).
hyperhomocysteinemia (1 paper, 2014). A serious metabolic condition caused by mutations in the MTHFR gene, medications, or nutritional deficiency. "Recent areas of study have focused on connexins, alterations in thrombomodulin, matrix Gla protein (MGP), Forkhead box protein C2 (FOXC2), hyperhomocysteinemia, and Type-I plasminogen activator inhibitor polymorphisms." (PMID 25520775, 2014).
IgA nephropathy (1 paper, 2026). "Transcriptomic-wide MR identified candidate genes across GN subtypes: RECQL, BRSK2, and MGP in acute GN; AFM, CFHR5, and EPHB2 in chronic GN; IL6R, MBL2, and PRSS3 in IgA nephropathy; and TIMP4, HCK, and PEAR1 in membranous nephropathy." (PMID 41990104, 2026).
infiltrating ductal carcinoma (1 paper, 2024). "In the latest research, MGP’s role in infiltrating ductal carcinoma (IDC) has yet to be fully explored, but it is related to its potential role in cell adhesion, proliferation and migration." (PMID 38627939, 2024).
inflammatory bowel disease (1 paper, 2021). A spectrum of small and large bowel inflammatory diseases of unknown etiology. "For instance, in our previous study, we found elevated dp-ucMGP levels in patients with inflammatory bowel disease (IBD), suggesting the involvement of MGP in IBD pathophysiology through inflammation process and disease activity." (PMID 34440481, 2021).
ischemic stroke (1 paper, 2020). A stroke disorder caused by obstruction of blood flow to the brain, due to thrombotic (local blood clot formation) or embolic (due to a blood clot or other material traveling from another site) event. "The MGP single nucleotide polymorphism (SNP) rs1800801 has previously been associated with recurrent ischemic stroke in a Spanish cohort." (PMID 32584873, 2020). "The AA genotype of the MGP SNP rs1800801 is associated with recurrence within the first year after ischemic stroke in North American Caucasians." (PMID 32584873, 2020). "With respect to prediction of recurrent ischemic stroke, it remains to be determined whether MGP SNP rs1800801 is a valid biomarker or surrogate marker." (PMID 32584873, 2020).
lymph node metastasis (1 paper, 2022). "According to the clinicopathological features, MGP overexpression was positively correlated with TNM classification and lymph node metastasis, whereas it was not significantly correlated with age, gender, tumor size, and differentiation." (PMID 35414780, 2022).
male infertile (1 paper, 2019). "In summary, our study demonstrates that the VK2-dependent protein MGP and its carboxylation enzyme GGCX play an essential role in epididymal sperm maturation and male fertility in rats and that the mutation of GGCX is associated with one form of human male infertility." (PMID 30981116, 2019).
malignant phyllodes tumor (1 paper, 2022). A phyllodes tumor with sarcomatous stroma. "Further verification of MGP is also required in sarcomas and malignant phyllodes tumors." (PMID 36284362, 2022).
meningioma (1 paper, 2023). A generally slow growing tumor attached to the dura mater. "Specifically, NF2 meningiomas expressed higher levels of arachnoid CLDN11 and pial LAMA2, while TRAF7 tumors overexpressed dural MGP and dural/arachnoid CRABP2 relative to NF2 tumors." (PMID 36937440, 2023).
metastatic tumors (1 paper, 2025). "In the metastatic tumors, our study predominantly found a significant increase in macrophages expressing CCL2, MGP, SPP1, and MMP9, which have been previously associated with tumor cell invasion, metastasis, and immunoresistance." (PMID 40858590, 2025). "In metastatic tumors, our study identified a significant presence of macrophages expressing CCL2, MGP, SPP1, and MMP9, which are associated with various aspects of tumor metastasis and may play a crucial role in preparing the metastatic niche for malignant cell growth." (PMID 40858590, 2025).
mineral bone disorder (1 paper, 2020). "These patients suffer from abnormalities in mineral metabolism, caused by an imbalance of calcification promoters (e.g., calcium and phosphate) and inhibitors (e.g., matrix Gla protein (MGP) and fetuin-A) and termed ‘mineral bone disorder’ (MBD)." (PMID 32183352, 2020).
mucinous ovarian cancer (1 paper, 2018). An invasive malignant neoplasm that arises from the ovary and is characterized by the presence of malignant epithelial cells that contain intracytoplasmic mucin and may resemble the epithelial cells of the endocervix or gastrointestinal tract. "Few cases of endometrioid, serous and mucinous ovarian cancer was analyzed to determine differences in MGP expression in various subtypes of cancer." (PMID 30257426, 2018).
neuropathy (1 paper, 2020). A disorder affecting the nervous system that manifests with pain, tingling, numbness, and/or muscle weakness. "We can suppose that the association between dp-ucMGP and neuropathy could directly result from MGP involvement in pathophysiology of diabetic peripheral neuropathy." (PMID 32092076, 2020).
ovarian serous carcinoma (1 paper, 2022). "Our results showed that only 2.4% of ovarian serous carcinomas had focal MGP expression, which is lower than the reported positivity of GATA3 (~6%,) and TRPS1 (14%,)." (PMID 36284362, 2022).
pancreatic adenocarcinoma (1 paper, 2022). "Further investigation of MGP expression in other tumor types is needed, especially those for which relatively high TRPS1 or GATA3 expression has been reported, such as salivary duct carcinomas and pancreatic adenocarcinoma." (PMID 36284362, 2022).
Pleural effusion (1 paper, 2025). The presence of an excessive amount of fluid in the pleural cavity. "In liver metastasis BL T cells, granzyme family genes (GZMA, GZMH, and GNLY) were enriched, while pleural effusion BL T cells showed increased TFF3, AGR2, MGP, and MIF expression." (PMID 39955556, 2025).
pulmonary emphysema (1 paper, 2024). A subcategory of chronic obstructive pulmonary disease (COPD). "Insufficient pulmonary MGP carboxylation hampers vascular calcification control, potentially causing pulmonary emphysema and decreased lung function." (PMID 38956732, 2024).
renal cell carcinoma (1 paper, 2022). "Consistently, we found that MGP was predominantly expressed in normal renal tubules, but the positivity rate significantly dropped to 5.0% in renal cell carcinomas." (PMID 36284362, 2022).
sarcopenia (1 paper, 2022). Progressive decline in muscle mass due to aging which results in decreased functional capacity of muscles. "Further work is needed to determine which MGP forms are biologically active and to identify the vitamin K-dependent and -independent actions involved in sarcopenia development." (PMID 36558558, 2022). "Since MGP is expressed and active in all three tissues mainly involved in sarcopenia development, it might be a good candidate as a biomarker in sarcopenia definition, especially since satisfactory molecules in this aspect are missing." (PMID 36558558, 2022). "MGP might also influence the development of sarcopenia via bone since it seems to be important in bone metabolism." (PMID 36558558, 2022). "Further studies with more sarcopenic persons and vitamin K measurements are needed to fully determine the usefulness of uc-dpMGP as a sarcopenia biomarker and to investigate whether other MGP isoforms might be possible biomarkers for sarcopenia characterization or definition." (PMID 36558558, 2022). "Several facts hint that MGP might be a promising biomarker candidate in sarcopenia." (PMID 36558558, 2022).
SOPH syndrome (1 paper, 2013). "Thus, an increased MGP activity would be compatible with a described short stature and associated bone defects present in the SOPH syndrome." (PMID 23828042, 2013).
spondyloepiphyseal dysplasia (1 paper, 2023). An osteochondrodysplasia that results in abnormalities of bone growth in the vertebral column and the epiphysis. "In the current study, we report four individuals from two unrelated families with previously undescribed spondyloepiphyseal dysplasia and heterozygous variants in the matrix Gla protein gene (MGP) affecting residue Cys19." (PMID 37923733, 2023).